S100A4 (S100 calcium binding protein A4)
Diseases named in the same sentence as S100A4 in open-access papers (continued):
Sharing a sentence is not in itself a finding about the gene and the disease.
cancer (continued). "The role of S100A4 in migration, invasion and metastasis as well as the impact of S100A4 expression levels on the overall prognosis of cancer patients have been documented in a broad range of different cancer entities." (PMID 26741489, 2016). "To determine whether these carcinomas cells had gained a mesenchymal phenotype, we performed S100A4 staining." (PMID 27323406, 2016). "On the contrary, cancer cells, fibroblasts and macrophages express strongly S100A4 1, 8, 14 and could constitute good extracellular sources of it for stimulating in vivo T cell motility and migration." (PMID 26734465, 2015). "Furthermore, β‐catenin has been shown to bind to this region and consequently increases the expression of the intracellular S100A4 protein, resulting in subsequent enhanced migration and invasion of cancer cells." (PMID 26734465, 2015). "Gli1 and S100A4 proteins localized almost exclusively to the neoplastic cells beside weakly positive staining of Shh in the islet cells and the chronic pancreatitic duct complex occasionally being seen in pancreatic tissues apart from cancer." (PMID 25072505, 2014). "In this regard, S100A4 is believed to have potential as a highly prognostic molecular biomarker for metastatic potential, as already shown for breast, colorectal, gallbladder, pancreatic as well as other types of cancer." (PMID 25310523, 2014). "Supporting Ring1B involvement in cancer progression, its strongest expression is found in those tumoral cells with nuclear expression of the metastasis-promoting protein S100A4 that invade the adipose tissue both in human IDC as well as in mammary gland xenografts." (PMID 24742605, 2014). "We can speculate that either there was S100A4 consumption in cancer tissue or inability to detect enhanced formation of S100A4 multimeric forms that occur during malignancy." (PMID 25359220, 2014). "In this article, we report the coincidence of the spatiotemporal expression pattern between MMPs and S100A4, a member of the S100 calcium-binding protein family largely known for its role in cancer cell metastasis, identified by our recent CaCl2-induced TAA animal study." (PMID 23922901, 2013). "S100A4 has been related to poor patient outcome in several cancer types." (PMID 24215488, 2013). "However, the biological function of S100A4 involved in the development and/or progression of cancers still remains poorly understood." (PMID 22200787, 2012). "Recent studies have shown that S100A4 may also contribute to cancer progression by enhancing cell survival functions." (PMID 22028766, 2011). "The reduction in S100A4 expression in the primary site may probably be related to cancer cells in the process of migration to distant sites." (PMID 18771601, 2008). "Having observed several presumably modified forms of S100A4 in cancer cells it was of interest to examine whether this was the case also in normal human cells." (PMID 18554396, 2008). "S100A4 has in numerous studies already been established as an important determinant of cancer metastasis, and potential PTMs may be of relevance for determining the biological processes resulting in increased metastatic capacity." (PMID 18554396, 2008). "These values represented a statistically-significant higher level of S100A4 mRNA in the liver metastases than in the primary cancer specimens when analyzed either as two groups (P<0.001, two-tailed Mann–Whitney U-Test) or as matched pairs (P<0.015, Wilcoxon Signed Rank Pairs test)." (PMID 11875708, 2002). "The results suggest that S100A4 may also have a normal role in cytotoxic immune reactions as well as in metastasis of carcinoma cells." (PMID 11875708, 2002). "The presence of S100A4 protein in the carcinoma cells was confirmed by immunocytochemical staining." (PMID 11875708, 2002).
cancer (continued). "Moreover 17 of the specimens of liver metastases also exhibited significant staining of the carcinoma cells (Fisher exact test, P<0.0001), however, only in one of the carcinoma specimens did the lymphocytes fail to stain for S100A4." (PMID 11875708, 2002). "Using competitive RT–PCR, the levels of S100A4 mRNA increase successively and significantly between normal tissue, carcinoma and liver metastases, and in every single matched case, the level of S100A4 mRNA is significantly higher in the liver metastases than the primary carcinoma." (PMID 11875708, 2002). "However, in the same study, it was found that the percentage of epithelial or connective tissue cells staining for S100A4 decreased with increasing malignancy grade amongst dysplastic lesions and carcinomas." (PMID 11875708, 2002). "Notably, this data indicates the possibility that E12 is applicable in treating not only CRC, but also in a wider range of clinical contexts such as other S100A4-prognostic cancers that display aberrant Wnt-signaling pathways, such as breast, ovarian, lung, gastric and melanoma cancer 55-59." (PMID 40765817, 2025). "Notably, there is a growing recognition of the interplay between S100A4, fibrosis, and cancer." (PMID 40078995, 2025). "In addition, we showed that S100A4 expression regulates T cell immunomodulatory function in cancer." (PMID 40078995, 2025). "Furthermore, additional studies are necessary to determine how and when targeting S100A4 in cancer synergizes with current, standard-of-care chemo, radiation, targeted, or immunotherapies such as anti-PD-1, anti-PD-L1, and anti-CTLA4, or CAR-T and other cellular therapies." (PMID 40078995, 2025). "Additionally, we found that ANXA9 could transfer the S100A4 out of cancer cells and down regulation of ANXA9 could decreased the cytokines of IL-6, IL-8, CCL2, and CCL5." (PMID 38609357, 2024). "Using these model systems, we have shown for the first time that a metastasis-inducing protein S100A4 which is widely expressed in most human cancers can be inhibited much more efficiently by converting a chemical inhibitor to a specific proteolysing agent inside the cancer cell." (PMID 37509135, 2023). "And MMP-2 and S100A4 may be the key targets of STAT3 involved in cancer metastasis." (PMID 35513871, 2022). "Therefore, S100A4 is the primary prognostic indicator of numerous types of cancer." (PMID 36499426, 2022). "Therefore, identifying the deleterious nsSNPs in S100A4 could help determine their influence, detrimental effects, and progression mechanisms of various cancers." (PMID 35965620, 2022). "However, whether intracellular S100A4 in macrophages also contributes to cancer malignancy by enabling TAMs to acquire M2-like protumor activity remains unknown." (PMID 34145030, 2021). "Thus, S100A4 upregulation in cancer cells highly metastatic to bone might be a key element in regulating bone metastasis." (PMID 33549040, 2021). "Giving its important role in metastasis, S100A4 may be a potential target for cancer therapy." (PMID 32842846, 2020). "Furthermore, our findings are essential to designing S100A4 analogs that may possibly act as effective blockers to inhibit the RAGE V domain-S100A1 route for the treatment of many kinds of human cancer and inflammation." (PMID 30779808, 2019). "However, injection of the cancer cells directly into bone also resulted in a lower cancer mass in mtMDA-S100A4sh-injected mice than in mtMDA-Csh-injected mice, suggesting that cancer-derived S100A4 modulates the bone microenvironment to support cancer cell growth." (PMID 31667000, 2019).
cancer (continued). "In addition, S100A4 expression is correlated with patients’ outcome and cancer metastasis." (PMID 30045697, 2018). "In addition, it has been reported that S100A4 may support MMP-9 and MMP-13 gene expression, and also that it may enhance the activity of some MMPs, causing higher cell dissociation and cancer metastasis." (PMID 30060564, 2018). "Therefore, S100A4 could be a candidate biomarker for defining cancer metastasis and useful target for therapy." (PMID 29069865, 2017). "Here we demonstrate that loss of post-transcriptional regulation of S100A4 due to epigenetic silencing of miR-505-5p and miR-520c-3p expression could be one of the main causes for the induction of S100A4 expression in CRC and other cancer entities." (PMID 28423501, 2017). "Thus, the detection of S100A4 protein expression could become a promising biomarker for the early diagnosis of cancer and in the prediction of cancer metastasis, raising the possibility of the development of S100A4 as a therapeutic target." (PMID 29069865, 2017). "Therefore, niclosamide might also be useful in the treatment of a variety of human cancers that exhibit alterations in the Wnt signaling and S100A4 overexpression." (PMID 29069865, 2017). "Although the precise mechanism by which S100A4 stimulates invasion and metastasis remains unknown, an extracellular role for S100A4 suggested by studies showing the secretion of S100A4 by cancer cells and the presence of S100A4 in the serum of cancer patients is intriguing." (PMID 23929008, 2014). "S100A4, also known as fibroblast-specific protein 1 (FSP1), is a small acidic calcium-binding protein that transduces Ca(2+)-signals via interaction with intracellular target proteins that has previously been described as a CAF marker associated with clinical outcome of cancer patients." (PMID 24039846, 2013). "However, S100A4 is also found in the extracellular environment, where it can be externalised from cancer cells and surrounding stromal and immune cells via an unknown non-coventional secretion pathway." (PMID 23469180, 2013). "Therefore, S100A4 has a role in both – cancer cells and endothelial cells – to increase malignancy." (PMID 21629247, 2011). "We instead found a translocation of S100A4 expression from cytoplasmic to nuclear in five samples with advanced disease stage, suggesting that S100A4 translocation to the nucleus may be related to the proliferation or metastatic potential of the cancer cells." (PMID 16265347, 2005). "Taken together, the expression of S100A4 seems to be rather stable in cancer cells, and one might suggest that signalling pathways regulating S100A4 gene transcription in cultured cancer cells are well defined, without extensive crosstalk between the different pathways." (PMID 12799648, 2003). "The percentage of specimens stained for S100A4 in the epithelial cells is significantly higher for those isolated from carcinomas and metastases than from the corresponding normal tissue, and from metastases than from corresponding carcinoma (Fisher Exact text, P<0.0016, P=0.04, respectively)." (PMID 11875708, 2002). "Thus, the possibility cannot be entirely eliminated that the appearance of S100A4 in the T cells of the appendix might have been, in some way affected by the presence of the carcinoma cells in the gut." (PMID 11875708, 2002). "Besides, it is also interesting to explore the relationship between S100A4 and other chemotherapeutic agents such as gemcitabine, flexibiotics, and vincristine, which may broaden the clinical applications of S100A4 knockdown, such as the treatment of other cancers and cytarabine high-dose therapy." (PMID 40584630, 2025). "It has been reported that S100A4 activates STAT3 in cancer cells, while proteomics results showed that overexpression of RP11-54O7.17 decreased intracellular S100A4 content." (PMID 41173847, 2025).
cancer (continued). "The S100A4 protein, previously referred to by multiple names including mts1, 18A2, CAPL, FSP1, metastasin, p9Ka, PEL98, and calgranulin, has attracted growing interest in oncology due to its crucial role in enhancing cancer cell proliferation and metastasis." (PMID 39796257, 2025). "For example, S100A4 promotes EMT and cancer stem cell properties, while S100A1 influences cell cycle arrest and apoptosis." (PMID 41303754, 2025). "CAFs educated by shSMYD3 or shCDCP1 cancer cells displayed a marked reduction in protein levels of α-SMA, FAP, PDGFRβ and S100A4 compared with shNC controls (densitometry, mean ± SEM; p < 0.001)." (PMID 41301830, 2025). "A: IHC detection of TGFβI and S100A4 expression in HCC (40×), TGFβI and S100A4 were highly expressed in cancer tissues." (PMID 40821652, 2025). "The two S100 genes S100A4 and S100A6, which are involved in many cellular processes including inflammation and cancer progression, were also highly expressed in the malignant T cells." (PMID 39169943, 2024). "Cluster 25 (CD163+ApoE+) macrophages expressed S100A4 and S100A10, while Cluster 18 (ApoE+ki67+) cancer cells expressed high levels of ApoE, Ki-67, and vimentin." (PMID 39695088, 2024). "The activity of phenylprolinederivatives also inhibits S100A4-NMII interactions in vivo and showsa reduction of cell migration in treated cancer cells." (PMID 39425667, 2024). "Detection of differential markers subtyped the cells of mesenchymal origin (vimentin, desmin, cadherin-11, podoplanin, CD74, S100A4, CD44, FAP), which vary according to the functional differentiation and specialization in sites of cancer tissue." (PMID 39575252, 2024). "S100 proteins, particularly S100A4, S100A7, and the S100A8/S100A9 heterodimer, are involved in cancer progression, inflammation, and metastasis through their interaction with RAGE." (PMID 39830522, 2024). "The immunosuppressive mechanism of NA can be described as follows: NA elevated the mRNA expression of ARG2, MMP1, S100A4, and RAPSN in granulocytes, thereby inhibiting the CKA of granulocytes and promoting cancer development." (PMID 36817446, 2023). "Niclosamide is an FDA-approved antihelminthic drug that suppresses glycemia; this drug has also been reported to inhibit cancer malignancy through various mechanisms, including Wnt/β-catenin, mTORC1, STAT3, NFκB, S100A4 signaling, and other signaling pathways." (PMID 36765890, 2023). "In order to indicated the role of the family members in HCC development, we further analyzed the expression of S100A4, S100A6, S100A10, S100A11 and S100A16 in pan-cancer, and the results suggested that they were highly expressed in most tumors." (PMID 37420211, 2023). "In contrast, ginsenoside Rg1 downregulated the mRNA expression of ARG2, MMP1, S100A4, and RAPSN, and upregulated the mRNA expression of LAMC2, DSC2, KRT6A, and FOSB, thereby enhancing the anti-cancer function of granulocytes inhibited by NA." (PMID 36817446, 2023). "Transcriptome sequencing analysis and qRT-PCR showed that NA elevated the mRNA expression of ARG2, MMP1, S100A4, and RAPSN in granulocytes, thereby reducing the anti-cancer function of granulocytes." (PMID 36817446, 2023). "The impact of the natural compound cantharidin and norcantharidin on S100A4 and MACC1 gene expression, cancer cell migration, motility, and colony formation in vitro was tested." (PMID 36674695, 2023). "Since both markers have been reported individually as stage-independent prognostic biomarkers across multiple cancer entities, we assessed the combined prognostic value of MACC1 and S100A4 for MFS and OS." (PMID 36008464, 2022). "One significant feature of these phenotype cancer cells was their high expression of mesenchymal markers, such as CDH2, S100A4, MMP2, WNT5A, and ZEB1." (PMID 36553542, 2022). "Metastasis-inducing S100A4 is a Wnt/β-catenin target gene and a prognostic biomarker for CRC and other cancer types." (PMID 35008201, 2021).
cancer (continued). "Because most of the S100 proteins have been considered as EMT facilitators in certain carcinoma cell lines, the present study showed that HE of AHNAK2 had a significantly higher proportion of S100A4, S100A8, and S100A9 expressions." (PMID 33918555, 2021). "Knocking down expression of S100A4 in AML lines results in cell death through induction of apoptosis and hence is an attractive target for cancer therapy particularly in AML given that normal cells would be spared." (PMID 31611628, 2020). "The expression of the Wnt/β-catenin pathway target genes, particularly those related to cancer, such as CD44, S100A4, MMP7, and LBH, was significantly increased in GC tumors compared with that in normal tissue." (PMID 30965636, 2019). "Fibroblast-specific protein 1 (FSP1), also named S100A4, was routinely used until it was shown to also be expressed by macrophages and cancer cells." (PMID 31547627, 2019). "To demonstrate its applicability we characterize how overexpression of S100A4, an intrinsic regulator of NMIIA filament assembly, modulates the contractility of epithelial carcinoma cells." (PMID 31652274, 2019). "When secreted extracellularly, S100a4 serves as a cytokine that regulates cell survival, migration, and differentiation and remodeling of ECM in cancer cells." (PMID 29910813, 2018). "S100A4 is often overexpressed in NSCLC as well as other tobacco-related malignancies, making it an excellent therapeutic target for lung and other cancers." (PMID 27127879, 2016). "Previous publications have shown that the degree of immunohistochemical staining of carcinoma cells for the proteins described, OPN, S100A4, S100P, AGR2 and FANCD2, reflect the level of each particular protein in the specimens." (PMID 27100728, 2016). "RT-PCR analysis revealed that IL-8 was upregulated by 10-fold in MDA-MB-231 cancer cells that were grown in 10% FBS, whereas S100A4 was down-regulated by 10-fold in cells maintained in 10% FBS." (PMID 25776572, 2015). "A recent report demonstrating the role of a Ca2+-binding protein, S100A4, in TG2-mediated migration further supports our observations of a Ca2+ requirement for TG2-mediated cancer cell migration." (PMID 24725450, 2014). "For example, S100A4, S100A6, S100A7 and S100B play oncogenic roles in cancer development, whereasS100B, S100A2, and S100A11 are believed as TSGs." (PMID 23894350, 2013). "In conclusion, for the first time, our work demonstrates the crucial link between two well-known important bio-markers for highly metastastic cancers, namely TG2 and S100A4." (PMID 23469180, 2013). "Our data reveal a novel potential strategy in cancer therapy, which is to antagonize the link between TG2 and S100A4 by inhibition of the crosslinking activity of TG2." (PMID 23469180, 2013). "Epithelial cells transitioning into myofibroblasts are also reported to express fibroblast specific protein-1 (FSP1, S100A4), which is used as a marker of EMT in fibrogenesis and cancer." (PMID 22973518, 2012). "Single-residue mutations that remove this synergy weaken binding and ameliorate the effects of S100A4 on NMIIA filament assembly and cell spreading in A431 human epithelial carcinoma cells." (PMID 22483112, 2012). "Increased expressions of S100A4 and MMP-9 are observed in human non-small cell lung cancer (NSCLC) and have significant correlations with clinical and biological behaviour of such cancer cells." (PMID 21970519, 2011). "On the other hand, in the EUS-FNA samples, the gene, CDK2A, CD44, S100A4 and MUC1 were specifically related to the 2nd clustering between cancer and non-cancer (p < 0.05)." (PMID 20416107, 2010). "After treatment of human carcinoma cells with interferon-gamma (IFN-γ), we observed downregulation of S100A4 both at mRNA and protein levels." (PMID 12799648, 2003). "Moreover, S100A4, S1PR5 and KLRG1, are biomarkers of therapeutic efficacy in mouse cancer models and patients with cancer." (PMID 40574416, 2025).